CIB4 (calcium and integrin binding family member 4)
Synonyms: KIP4
Tractability: No criterion of Open Targets' tractability assessment is met for any kind of drug.
Gene: Protein-coding gene on chromosome 2 (26,581,205 to 26,641,366, reverse strand). Ensembl gene ENSG00000157884.
Gene Ontology:
Molecular function: calcium ion binding; magnesium ion binding; protein binding
Genetic constraint (gnomAD): Loss-of-function variants: 18 observed, 18.31 expected, observed/expected ratio (o/e) 0.98, 90% interval 0.68 to 1.46. The upper end of that interval is the gene's LOEUF score, 1.46, which puts it in group 6 of 6, group 1 being the genes least tolerant of losing a copy. Missense variants: 157 observed, 150.99 expected, observed/expected ratio (o/e) 1.04, 90% interval 0.91 to 1.19. Synonymous variants: 49 observed, 56.35 expected, observed/expected ratio (o/e) 0.87, 90% interval 0.69 to 1.1.
Homologues: Orthologues: chimpanzee CIB4 (99% identical), pig CIB4 (94% identical), rat Cib4 (94% identical), dog CIB4 (93% identical), guinea pig CIB4 (92% identical), mouse Cib4 (92% identical), rabbit CIB4 (92% identical), macaque CIB4 (83% identical), Caenorhabditis elegans calm-1 (39% identical), Drosophila melanogaster Cib2 (38% identical), Caenorhabditis elegans chpf-1 (27% identical), Caenorhabditis elegans chpf-2 (25% identical), and 3 more. Paralogues in human: CIB1 (43% identical), CIB2 (38% identical), CIB3 (35% identical), CHP2 (24% identical), PPP3R2 (24% identical), TESC (24% identical), CHP1 (23% identical), PPP3R1 (23% identical).
Diseases named in the same sentence as CIB4 in open-access papers:
CIB4 is named in the same sentence as 5 diseases in open-access papers, as found by Europe PMC text mining. Sharing a sentence is not in itself a finding about the gene and the disease. The quoted sentences say what the papers report.
Infertility (2 papers, 2020 to 2025). "Similar to CIB1-knockout mice, Cib4-knockout mice exhibited impaired haploid differentiation during spermatogenesis and infertility." (PMID 40076845, 2025). "Together, these findings highlight the critical role of CIB1 and CIB4 in male fertility and their potential involvement in infertility." (PMID 40076845, 2025).
Azoospermia (1 paper, 2020). Absence of any measurable level of sperm,whereby spermatozoa cannot be observed even after centrifugation of the semen pellet. "Elucidating the function of Cib4 in spermatogenesis may lead to better treatment of individuals with azoospermia." (PMID 32430498, 2020).
male infertility (1 paper, 2020). The inability of the male to effect fertilization of an ovum after a specified period of unprotected intercourse. "To investigate the cause of male infertility, we observed testes of Cib4+/−7and Cib4–7/−7 adult male mice and found that the average testis weight of Cib4–7/−7 mice is smaller than that of Cib4+/−7 mice." (PMID 32430498, 2020). "Further analysis of CIB4 function may shed light on the etiology of male infertility caused by spermatogenesis defects, and CIB4 could be a target for male contraceptives because of its dominant expression in the testis." (PMID 32430498, 2020). "Cib4 mutant mice exhibit male infertility due to impaired spermiogenesis." (PMID 32430498, 2020).
CIB4 also shares sentences with these, for which no sentence is quoted: COVID-19 (1 paper); tumor (1).